RAC1 (Rac family small GTPase 1)
Diseases named in the same sentence as RAC1 in open-access papers (continued):
Sharing a sentence is not in itself a finding about the gene and the disease.
cancer (continued). "Understanding the impact of group I PAKs and PAK1 and Rac1 to cell mechanics and invasion can lead to identification of mechanotransduction processes for future treatments to modify cell migration under certain circumstances, such as cancer metastasis or wound healing processes after tissue injury." (PMID 32047750, 2020). "Interestingly, deregulation of Rac1 has been recently found in a variety of cancers." (PMID 32585958, 2020). "Some of these diverse mechanisms for calmodulin to regulate KRas and Rac1 GTPases could provide therapeutic opportunity in cancer pathophysiology, in particular where aberrant KRas signalling drives Rac1-dependent activities that contribute to tumour progression." (PMID 32456244, 2020). "Thus targeting α2β1 integrin and/or the development of Rac1-independent genotoxic agents may enhance anti-cancer treatment." (PMID 31857649, 2019). "Therefore, strategies to increase the expression and/or activity of RAC1B, or its generation by alternative splicing from RAC1 may be worth testing in cancers in which TGF-β1 drives invasion and metastatic dissemination." (PMID 31108998, 2019). "Interestingly, research on the use of Rac1 inhibitors in the case of common and/or aggressive tumors showed that Rac1 could be a good target for counteracting cancer progression." (PMID 31035701, 2019). "Importantly, aberrant Rac1 activation also occurs in other deadly human diseases (most notably cancer and cardiovascular disease), so that development of clinically-suitable Rac1 inhibitors continues to be a highly pursued goal with potential implications for the field of HIV therapeutics." (PMID 29401736, 2018). "Notably, while these studies used GTPase‐deficient G14V or Q63L in RhoA and G12V or Q61L Rac1 analogous to oncogenic Ras mutations, such mutations in Rho GTPases have not been detected in clinical cancer." (PMID 29749605, 2018). "In addition to regulating actin cytoskeleton remodeling necessary for tumor cell adhesion, migration and invasion, Rac1 through its downstream effectors, regulates cancer cell survival, tumor angiogenesis, phenotypic plasticity, quiescence, and resistance to therapeutics." (PMID 30261690, 2018). "Thus, by promoting the degradation of nuclear Rac1, statins might also be beneficial for targeting cancer metastasis." (PMID 27442895, 2017). "This, together with the fact that it can also bind to the constitutively active splice variant Rac1b, suggest that this type of Rac1 inhibition might prove beneficial for targeting Rac1 activating mutants that have recently been described in a number of cancer types." (PMID 27442895, 2017). "Along this line, the fact that we found the C-terminal polyproline-rich region of 28 amino acids to be responsible for binding to PAK1 may provide a starting point for evaluating peptide-based inhibitors that block the Rac1 signaling pathway in endometrial and possibly other types of cancers." (PMID 27760566, 2016). "Therefore, our findings that GLS2 binds to and inhibits Rac1 raised the possibility that GLS2 may play an important role in suppressing cancer metastasis." (PMID 26751560, 2016). "Rac1-GTPase is known to promote lamellipodia formation at the leading edge of migrating cells, which are involved in cancer metastasis, this may accounts for the phenomenon that TIPE2 expression was decreased markedly in tumor cells that infiltrated into the stroma." (PMID 27556698, 2016). "Furthermore, RAC1 is involved in gonadotropins expression, cytokine transcription and actin reorganization, which play a critical role for proliferation, migration and evading apoptosis of cancer cell." (PMID 26989626, 2016). "In addition to E-cadherin downregulation, Twist1 may contribute to the development of a motile mesenchymal-like cancer cell phenotype through the activation of RAC1 (Ras-related C3 botulinum toxin substrate 1), a small G-protein of the Rho family." (PMID 27074574, 2016).
cancer (continued). "Therefore, this study provides insight into previously unreported P-Rex1-Rac1 cellular functions that mediate cell migration and highlights additional modes by which P-Rex1 and Rac1 might drive cancer dissemination." (PMID 26887924, 2016). "The activation of Rac1 activation in tumors might play a role in cancer progression." (PMID 26716504, 2016). "This study could be valuable to clarify the Rac1 role in cancer." (PMID 26933917, 2016). "As with Rac1, no mutations in RhoA had been detected in human cancers until very recently." (PMID 27104658, 2016). "Interestingly, Twist1 can elicits cancer movement through activation of Rac1 GTPase." (PMID 25868853, 2015). "We hypothesized that nestin/CDK5/Rac1 signaling behaves different in early and advanced cancer." (PMID 25371063, 2015). "Thus, activation of Rac1 contributes to the migration, invasion, and metastasis of cancers." (PMID 25136657, 2014). "Furthermore, it is suggested that blocking Rac1-related pathways in treatment-resistant HNSCC cells enriched in CSC subpopulations could also diminish processes of neovascularization within malignant tumors." (PMID 25594058, 2014). "Consequently, we hypothesize that Rac1/Cdc42 inhibition by AZA1 treatment increases cancer cell apoptosis involving the PAK-AKT-BAD signaling pathways." (PMID 24040362, 2013). "Since IQGAP1 has been shown to associate with various small GTPases including cdc42 and Rac1, we examined whether or not RalA, previously shown to signal downstream of β-arrestin in cancer cells, can associate with IQGAP1." (PMID 23405264, 2013). "However, there are no other reports on the association of 14-3-3 and Rac1-GTPases in the regulation of cell migration of any cancer cells." (PMID 22808202, 2012). "To examine whether the observed inhibition of proliferation of the overall cancer cell population by Rac1 knockdown is due to a specific effect on CSCs, we next tested the growth properties of isolated SP and non-SP cells before and after transduction of Rac1-specific shRNA." (PMID 21347385, 2011). "Therefore, the role of active Rac1 GTPase and its downstream effector needs to be studied by using surgically resected samples of human tumors to better assess their contribution to human cancer." (PMID 20426825, 2010). "Furthermore, our study elucidates that the expression of several highly significant cancer related genes require the activities of Rac1 and/or Cdc42 which may also play a critical role in cellular transformation." (PMID 20067638, 2010). "Therefore, several oncogenic pathways may act through Pak1 to promote cancer progression, so that Pak1 protein expression had a greater impact on overall and recurrence-free survival than Rac1 activity in the present study." (PMID 20426825, 2010). "Global transcriptome Pathway RespOnsive GENes for activity inference (PROGENy) analysis on PECAPJ41CLONED2-RAC1 mutant stable cells (vs. EGFP- and RAC1-WT-expressing cells) demonstrated perturbation of 14 important cancer signaling pathways." (PMID 39941730, 2025). "We have shown previously that the PCAIs suppress the levels of RAC1, RHOA, and CDC42 in cancer cell lines." (PMID 40736275, 2025). "Here, we showed that RAC1-altered HNSCCs, particularly in HPV(−)HNSCC settings, are highly aggressive cancers that negatively impact patient clinical outcomes." (PMID 39941730, 2025). "The signaling pathway involving Rac1 and PAK1 frequently exhibits overactivation across various cancer types." (PMID 40867609, 2025). "PAK1 and its eponymous activator RAC1 (also known as p21RAC1) are important components of signaling by oncogenic RAS proteins and represent a targetable vulnerability in cancer cells driven by RAS oncogenes." (PMID 41154654, 2025). "Gene groups linked to efferocytosis, including Tyro3, Axl, MerTK, Gas6, BAI-1, CX3CL1, CD31, CD47, Rac1, and the TIM family, represent significant targets for prospective cancer therapies." (PMID 39911848, 2025).
cancer (continued). "PAK1 (p21-activated protein kinase) and its eponymous activator RAC1 (also known as p21RAC1) are important components of signaling by oncogenic RAS proteins and represent a targetable vulnerability in cancer cells driven by RAS oncogenes." (PMID 41465386, 2025). "Integrin β4, relying on the regulation of TNFAIP2 and IQGAP1, effectively activated RAC1, promoting the migration of TNBC cells while enhancing the resistance of cancer cells to DNA damage-related therapies." (PMID 40830812, 2025). "Thus, RAC1-amp/gain status may determine Rac inhibitor sensitivity in pan-cancers, including HNSCC." (PMID 39941730, 2025). "To explore the correlation between RAC1 expression and genomic alterations, we examined data on RAC1 expression and CNV status across 33 types of cancers." (PMID 39898257, 2025). "The synergistic action of NaV1.5 and Rac1 is often accompanied by the activation of MMPs, which promote the breakdown of the ECM, making it easier for cancer cells to invade surrounding tissues." (PMID 39673684, 2025). "The action of UA leads to a reduction in Rac1 activity and PAK1 phosphorylation, which contributes to the inhibition of cancer." (PMID 40867609, 2025). "CXCR4+ cancer stem cells also show increased tumor invasion and cell migration, via the activation of Rac1 and MMP-2/MMP-14 proteinases and enhanced angiogenesis by triggering cancer cell adhesion to endothelial cells and upregulation of VEGF/VEGFR." (PMID 40307933, 2025). "We also showed that A41 interferes with the binding of guanine nucleotides on RAC1 and provided evidence for the pharmacological/therapeutic potential of this RAC inhibitor in invasive human cancers such as TNBC." (PMID 40633540, 2025). "In the current study, we thoroughly examined the mRNA levels of NCKAP1, SLC7A11, WASF2, RAC1, SLC3A2, and RPN1 as well as the relationships between the mRNA levels of these six genes in pan-cancer." (PMID 38968580, 2024). "Downstream of active KRAS, hyperactivation of the small GTPase RAC1 drives proliferation and cytoskeletal remodelling in PDAC and other cancers." (PMID 38712822, 2024). "The remaining eight target genes (CFL1, FNBP4, NDUFB3, OCIAD2, PLIN3, POU2AF1, RAC1, TMEM141) presented a combined influence in five or fewer cancer types." (PMID 39201394, 2024). "Recent studies have shown that Ldha interacts with Rac1, a GFP enzyme of the Rho family, to regulate cancer cell proliferation.[45a,b] Our data also show that Ldha interacts with Rac1 in neural progenitor cells." (PMID 39033542, 2024). "The in vitro study of the signaling chain whereby RAB4A impacts cancer cell stemness has demonstrated that NUMB, NOTCH1, RAC1, and SOX2 are essential in mediating the regulatory effects of RAB4A on CSCs in multiple cancer cell lines of diverse tissue origins." (PMID 39463384, 2024). "Disruption of the NEK2–RhoGDI1 interaction through overexpression of a RhoGDI1 truncated fragment (aa 112–134) led to diminished RhoGDI1 phosphorylation and RhoA/Rac1 activation induced by NEK2, resulting in reduced cancer cell proliferation and migration." (PMID 39768163, 2024). "RAC1 and RAC1B have been proposed as potential targets for cancer therapies since both can play a role in many different aspects of tumor biology and therapy resistance." (PMID 39001533, 2024). "Using in vitro and in vivo studies, we show that RAB4A, as the upstream regulator, relays signal stepwise to NUMB, NOTCH1, RAC1, and then SOX2 to control the self-renewal property of multiple cancer cells of diverse tissue origins." (PMID 39463384, 2024). "A key revelation is that CGN c.3560C > T triggers the overexpression of IQGAP1 and activates Rac1-dependent EMT, thus promoting cancer cell behavior." (PMID 38424547, 2024). "CPYPP, a DOCK (dedicator of cytokinesis) inhibitor known for its anti-cancer effects by disrupting the interaction between DOCK2 and Rac1, as well as CsA and curcumin, induced significant cytoplasmic vacuolization." (PMID 38858714, 2024).
cancer (continued). "In the previous study, we found RAB4A to be a major upstream regulator of RAC1 activation on EMT and cancer stemness." (PMID 39463384, 2024). "Compared to RAC1, RAC1B has been shown to activate different signaling pathways that can contribute to differences in cancer cell phenotypes if the cells overexpress RAC1 or RAC1B." (PMID 39001533, 2024). "An OCSCC cohort more than twice the size of the TCGA cohort allowed us to find additional cancer driver genes that are frequently affected in CNA-quiet OCSCC, notably PIK3CA, RAC1, and TERT, besides the previously established HRAS and CASP8." (PMID 39428388, 2024). "In summary, these studies conclude that NOTCH1, through its activation product NICD, forms a necessary link in the RAB4A signaling axis upstream of RAC1 and SOX2 in promoting the cancer cell stemness/self-renewal property." (PMID 39463384, 2024). "PI3K and MAPK proteins as well as RAC1 BCL2 and PPIA were found to be overexpressed between cancer tissues and healthy controls." (PMID 39409902, 2024). "RAC1, BAX, EEF1E1, and LPCAT1, four highly interacted genes, showed differential expression at gene levels in HCC and played essential roles in cancer cells." (PMID 37999208, 2023). "Since GEF-induced activation is the most common mechanism for Rac1 activation, the development of Rac1 GEF inhibitors is a promising strategy in cancer therapy." (PMID 37049739, 2023). "Following the administration with mangiferin, this cancer cell decreased Rac1/Cdc42, WAVE2, phospho-Rac1/Cdc42, Arp2, and Arp3." (PMID 38137424, 2023). "EHop‐016, the RAC1 and RAC3 dual‐target inhibitor, has the potential as an anti‐cancer compound to block cancer progression via multiple Rac‐directed mechanisms." (PMID 37386813, 2023). "As EGF receptor, Vav1, RhoA, Rac1, and BPGAP1 are all associated with oncogenesis and/or cancer metastasis, the identification of this novel EGFR-BPGAP1-Vav1-Rac1-RhoA signaling axis could provide new approaches to a combinatorial therapeutic intervention in cancer progression." (PMID 36598812, 2023). "Understanding how the prenylation and localization of small GTPases such as RAC1 and RAC1B are regulated will help define new strategies to target small GTPases in various diseases, including cancers and neurologic or cardiovascular disorders." (PMID 37059183, 2023). "Apart from cancer cells, we were also able to confirm that ERK3 sustains the activity of RAC1 and CDC42 in primary human umbilical vein endothelial cells, HUVECs." (PMID 37057894, 2023). "Third, while observing the well-studied role of splicing differences for RAC1 and KRAS in cancer patients, we discovered several other recurring differences in genes, including multi-cancer-associated RAMSEF splicing change." (PMID 36467401, 2022). "This study identifies an involvement of RAB4A, through its regulation of RAC1 activation, in the regulation of EMT, stemness and invasion—all major characteristics of cancer progression, and ultimately patient survival." (PMID 36307864, 2022). "RAC1/CDC42 also promotes HCC EMT and metastasis via PAK1, which induces cancer metastasis via the phosphorylation of paxillin and activation of JNK." (PMID 36348464, 2022). "Increased cytoplasmic Ca2+ levels enhance PKA, ERK, Rac1, and ROCK activity, which have the potential to promote cancer cell survival and migration." (PMID 35646889, 2022). "The essential downstream regulator of RAC1 and CDC42 is PAK, which plays vital roles in cancer initiation, growth, angiogenesis, immunity, metabolism, metastasis, and drug resistance." (PMID 35433481, 2022). "To evaluate the broader applicability of the newly-discovered relationship between RAB4A and RAC1 in regulating EMT and cell invasion, we expanded the study to other cancer cell lines." (PMID 36307864, 2022). "Of great interest should be research to evaluate the potential of oncolytic NDV in targeting the many downstream pathways controlled by Rac1 and to compare this with SMI leads in cancer drug development." (PMID 35327364, 2022).
cancer (continued). "These 50 drugs were also found to be validated in different cancer cell lines, such as dasatinib, captopril, leflunomide, and dextromethorphan targeting SRC, MMP2, PTK2B, and RAC1 hub genes, respectively." (PMID 35456223, 2022). "Conversely, RAC1 can be inhibited by miR-365 and miR-194, leading to the suppression of HCC dedifferentiation and cancer stem cell proliferation." (PMID 36348464, 2022). "In support of these findings, HCC patients with higher levels of RAC1, CDC42, and PAK1 show worse overall survival, which can be attributed to enhanced macropinocytosis and resistance to cancer therapy." (PMID 35287706, 2022). "Mechanistically, this study identifies RAB4A as an upstream regulator of RAC1 activation, through which RAB4A performs these regulatory functions in cancer signaling and major cancer phenotypes." (PMID 36307864, 2022). "Ras-related C3 botulinum toxin substrate one gene (RAC1) has two isoforms that change the sequence of the protein (RAC1 and RAC1B), with differential risks to cancer progression." (PMID 36467401, 2022). "Introducing activated RAC1 efficiently rescued EMT gene expression, invasion and tumor formation suppressed by RAB4A knockdown in both the in vitro and in vivo cancer models." (PMID 36307864, 2022). "RAC1, a key member of the RHO family of small GTPases, has known roles in cancers such as transformation, invasion, angiogenesis and survival." (PMID 36307864, 2022). "The active form of RAS, RAC1, and CDC42 has been reported to facilitate the acquisition of various cancer hallmarks, notably proliferation, migration, invasion, and metastasis via upregulation of EMT." (PMID 33758996, 2022). "OGR1-induced up-regulation of CK2αP through activation of small GTPase, Rac1/cdc42, and ERK/JNK/p38 pathways are responsible for inhibition of cancer cell migration." (PMID 35123428, 2022). "Within cancer, splicing changes in small GTPases have been noted for genes including NRAS, KRAS, HRAS, and RAC1 (Rásó, 2020)." (PMID 36467401, 2022). "RAC1 cycles between a GDP-bound inactive form and a GTP-bound active form and is activated by multiple mechanisms in various cancers." (PMID 34373577, 2021). "While in some cancer cell lines TRPV2 seems to have a positive impact on cancer cell migration, the interplay between TRPV2 and RhoA/Rac1 seems to suppress invasion of Fibroblast-like Synoviocytes (FLS cells)." (PMID 34356643, 2021). "Enhanced ROS production leads to IQGAP1 and Rac1 interaction that overexpressed Rac1 induces Src/FAK signaling via phosphorylation to promote migration and invasion of cancer cells, and stimulate anoikis resistance." (PMID 33921908, 2021). "Since RAC1 was increasingly translocated to the nucleus in cancer cells, we subsequently examined the spatio-temporal coordination of EGFR with RAC1." (PMID 34741044, 2021). "NSC23766, the first selective RAC1-GEF blocking agent discovered, inhibits RAC1 interaction with TIAM1 and TRIO, countering RAC1 tumorigenic effects in several cancer models." (PMID 34827551, 2021). "Mechanistically, the study suggested that constitutive signaling from DR5 promotes activation of a Rac1/PI3K/Akt signaling axis that increases migration and invasion in a cancer cell-autonomous manner." (PMID 33810241, 2021). "Here, using evidence from computer modeling, deletion analysis, reciprocal immunoprecipitation, and PLA, we revealed that RAC1 directly interacts with IMPDH2, recruiting it to cell membrane protrusions that are pivotal for cancer cell invasion." (PMID 34667203, 2021). "Mechanically, overexpression of ARHGAP25 inactivated AKT/mTOR signaling pathway by regulating Rac1/PAK1 signaling, which was in line with the results from the Gene set enrichment analysis on The Cancer Genome Atlas dataset." (PMID 33994864, 2021). "We will focus in particular on five members of the RHO GTPase family, including RHOA, RHOB, RHOC, RAC1, and CDC42, to illustrate the role of lncRNAs in cancer progression." (PMID 34771549, 2021).